EGFR (epidermal growth factor receptor)
Diseases named in the same sentence as EGFR in open-access papers (continued):
Sharing a sentence is not in itself a finding about the gene and the disease.
kidney disease (34 papers, 2013 to 2025). "Overall, these data implicate cluster 5 cells in kidney deregulation, as HNF1B mutations are associated with kidney diseases and EGFR plays a major role in the development of kidney fibrosis." (PMID 39918986, 2025). "Deficiency in EGF and TGF-α signaling through EGFR has been shown to be an important modifier of kidney structure and function and a risk factor in renal diseases." (PMID 36752209, 2023). "PTPRG interacts with epidermal growth factor receptor (EGFR), a protein tyrosine kinase containing several phosphorylation sites, and dysregulated EGFR expression has been linked to renal disease." (PMID 34389752, 2021). "Similar anti-fibrotic effects of EGFR blockade have been also observed in other murine models of kidney diseases including angiotensin II-infused mice." (PMID 41318746, 2025). "A metaanalysis of glomerular transcriptomic characteristics of human and mouse samples of kidney diseases indicated a central role for the EGFR in both species." (PMID 36359813, 2022). "A recent study further demonstrated a role for the EGFR/YAP-signaling in therapeutic responses to the renal diseases." (PMID 33622361, 2021). "Epidermal growth factor receptor (EGFR) and tumor necrotic factor-α (TNF-α) play important roles in renal hemodynamics, and they have been reported to be associated with some renal diseases." (PMID 34501555, 2021). "Collectively, EGFR signaling presents an interesting therapeutic target in the treatment of fibrotic renal disease." (PMID 32661331, 2020). "Many preclinical studies have shown that the epidermal growth factor receptor (EGFR) can be a potential therapeutic target for renal diseases, as we will review here." (PMID 30670929, 2018). "Intensive research in many experimental studies has shown that EGFR blockade exerts beneficial effects in progressive kidney disease, mainly ameliorating fibrosis." (PMID 30670929, 2018). "EGFR inhibitors have been found to alleviate angiotensin 2-induced kidney disease, suppressing inflammation and oxidative stress." (PMID 27014908, 2016). "Experimental studies have shown that genetic or pharmacological EGFR blockade ameliorates renal disease progression, mainly by diminishing kidney fibrosis." (PMID 26064952, 2015). "Emerging evidence suggests that blockade of epidermal growth factor receptor (EGFR) can be a therapeutic option for renal diseases." (PMID 26064952, 2015). "However, the toxicity of EGFR inhibitors, especially skin toxicity, hampers their use for kidney disease." (PMID 40165104, 2025). "In summary, the Ureteral accessible chromatin regions may affect the treatment of kidney disease through regulation of the EGFR-TKIs resistance genes." (PMID 40034749, 2025). "Last, a body of literature has shown a critical role of EGFR in the progression of kidney disease." (PMID 40165104, 2025). "However, the impact of combining EGFR-clocking drugs with STAT3 inhibitors in kidney diseases remains to be tested." (PMID 39335615, 2024). "Similarly, EGFR holds therapeutic significance in case of diabetic complication leading to Kidney disease, for OA, and TNBC." (PMID 39281650, 2024). "Better insights in EGFR signaling in renal disease could improve our current knowledge of renal pathology contributing to therapeutic strategies for CKD development and progression." (PMID 30670929, 2018). "Several experimental studies have suggested that blocking EGFR could be an important tool to treat kidney diseases, especially by regulating inflammation, cell proliferation, and fibrosis." (PMID 30670929, 2018). "Genetic or pharmacological EGFR blockade slows experimental renal disease progression." (PMID 28060743, 2017). "In humans, EGFR has been reported as an important player in pathways of kidney diseases." (PMID 27881077, 2016).
skin disorder (29 papers, 2014 to 2026). Any deviation from the normal structure or function of the skin or subcutaneous tissue that is manifested by a characteristic set of symptoms and signs. "EGFR‐TKI‐induced skin disorders include papulopustular rush, hair loss, eye/eyelash abnormalities, periungual/nail alterations and xerosis/pruritus." (PMID 38379420, 2024). "Skin disorders are the most common side effect associated with epidermal growth factor receptor‐tyrosine kinase inhibitor (EGFR‐TKI) therapy." (PMID 38379420, 2024). "The clinical use of polydatin in skin disorders is also supported by the evidence that interleukin-8 (IL-8) plays a key role in inducing cutaneous AEs associated with anti-EGFR treatment, since polydatin is known to regulate IL-8 gene expression." (PMID 33530427, 2021). "The skin disorders caused by afatinib are common to all EGFR-TKIs and anti-EGFR antibody drugs in general." (PMID 32252690, 2020). "The drug-induced skin disorders of EGFR-TKIs are side effects caused by TKI inhibiting EGFR localized in the skin." (PMID 32252690, 2020). "The present results suggest that application of minocycline is effective for the prevention and repair of skin disorders caused by afatinib, one of EGFR-TKIs." (PMID 32252690, 2020). "We report that AboundTM was apparently effective in the treatment for anti-EGFR antibody-associated skin disorder." (PMID 24517087, 2014). "Epidermal growth factor receptor (EGFR) antibodies (panitumumab and cetuximab) and EGFR tyrosine kinase inhibitors (TKIs; gefitinib, erlotinib, afatinib, osimertinib, and dacomitinib) cause various skin disorders." (PMID 40888993, 2025). "If the skin disorder caused by EGFR‐TKI is more severe, the side effects of adapalene may be more pronounced, and it is important to treat this inflammation with a moisturizer or other combination therapy." (PMID 38379420, 2024). "Furthermore, considering that the degree of skin disorders caused by anti-EGFR drugs correlates with survival probability, it is imperative that the skin disorders be properly controlled to avoid treatment discontinuation." (PMID 36045384, 2022). "With regard to the skin disorders, when compared to gemcitabine alone, the higher risk was observed in the combination fluoropyrimidine and gemcitabine, as well as in the combination of EGFR inhibitors and gemcitabine." (PMID 31703359, 2019). "Thus, skin barrier function may have been reduced in these patients with high body weight, potentially increasing their susceptibility to skin disorders caused by anti-EGFR antibody drugs." (PMID 36045384, 2022). "Taken together, these results suggest that adapalene can partially ameliorate EGFR‐TKI‐induced skin disorders by downregulating AQP3." (PMID 38379420, 2024). "Developing an effective means to predict the severity of skin disorders in patients prior to treatment with anti-EGFR antibody drugs will facilitate the timely administration of preventive or early measures." (PMID 36045384, 2022). "While epidermal growth factor receptor (EGFR)-tyrosine kinase inhibitors (TKIs) exert a breakthrough effect, the incidence of skin disorders as a side effect has significantly reduced patients’ quality of life." (PMID 32252690, 2020). "The symptomatic treatment was continued; however, at the end of the ninth course of the anti-EGFR antibody therapy, the skin disorder was observed on both the lower limbs as well as on the face remarkably." (PMID 24517087, 2014). "During the second course of the anti-EGFR antibody therapy, skin disorder appeared on the patient’s facial surfaces and gradually on other parts." (PMID 24517087, 2014). "It is important to control skin disorders since they can hinder further EGFR‐TKI treatment." (PMID 38379420, 2024). "An appropriate dose of adapalene may be beneficial for the treatment of skin disorders induced by EGFR‐TKIs." (PMID 38379420, 2024).
skin disorder (continued). "Therefore, the aims of this study were to analyze the effect of adapalene on EGFR‐TKI‐induced skin disorders and to clarify the mechanism of action of adapalene." (PMID 38379420, 2024). "We suggest that adapalene may be a possible treatment option for skin disorders induced by EGFR‐TKIs." (PMID 38379420, 2024). "Ameliorating skin disorders is very important for the continued administration of EGFR‐TKIs." (PMID 38379420, 2024). "One of the most general adverse events of anti-EGFR monoclonal antibody therapy is skin disorder." (PMID 24517087, 2014). "In the future, prospective studies of AboundTM in patients treated with anti-EGFR antibody is necessary, but our report indicates that AboundTM may have the potential to support nutritional status and to improve skin disorder." (PMID 24517087, 2014). "Although epidermal growth factor receptor-targeted monoclonal antibodies are known to cause skin disorders, this study alone could not determine which regimens or durations contributed to an increased risk." (PMID 41298770, 2025). "Initially, for gefitinib, which was the first approved EGFR-TKI for NSCLC treatment, the AEs were limited to relatively minor events, such as skin disorders." (PMID 33466795, 2021). "This study aimed to develop a treatment for inflammatory ulcers as one of the side effects of afatinib (Giotrif®), a second-generation EGFR-TKI, and established a skin disorder mouse model to investigate the protective effect of minocycline." (PMID 32252690, 2020).
bacterial infection (28 papers, 2010 to 2025). "Adapalene upregulates the expression of antimicrobial peptides, which may reduce the risk of bacterial infections that contribute to the skin damage caused by EGFR‐TKIs." (PMID 38379420, 2024). "To determine the effect of airway epithelial cell-specific EGFR deletion on the clearance of spontaneous bacterial infections, we estimated airspace bacterial burden by determining the colony-forming unit (CFU) counts in BALF at PND21." (PMID 40406132, 2025). "Both aging and bacterial infections are known to activate EGFR and JAK-STAT signaling, but the molecular mechanisms underlying these responses are poorly understood." (PMID 39594605, 2024). "For example: bacterial infection can activate EGFR-Ras signaling in precursor cells, inducing upd expression, while activation of EGFR-Ras signaling in ECs upregulates upd3 expression." (PMID 39594605, 2024). "Specifically, our study has shown that bacterial infection of hBMECs is able to induce a ligand-dependent transactivation of EGFR, which requires the ADAM17-mediated cleavage and release of HB-EGF." (PMID 30687645, 2018). "When the bacteria infect the host cell, the ALP combines with EGF, thus effecting the EGFR pathway and accelerating bacterial infection of the host cell." (PMID 28184355, 2017). "As an important clinical therapeutic target and the signaling receptor on the cell surface, EGFR has been investigated in multiple bacterial infections." (PMID 27756321, 2016). "Aberrant activation of this response by impairment of the EGFR-driven pathway may lead to the establishment of a pro-inflammatory milieu in the skin and presumably in other epithelia, eventually precipitating unwanted tissue damage and susceptibility to bacterial infections." (PMID 27322144, 2016). "The activation of the EGFR pathway in progenitor cells led us to examine the role of this pathway in controlling ISC activity upon bacterial infection." (PMID 21176204, 2010). "We further demonstrate that the EGFR pathway is central to these three steps following bacterial infection." (PMID 21176204, 2010). "For example, it undergoes phosphorylation by tyrosine kinases such as EGFR (Epidermal Growth Factor Receptor), which activates signaling pathways like NF-κB, primarily involved in bacterial infection responses, and the MAPK/ERK pathway, which regulates cell proliferation under stress conditions." (PMID 40699655, 2025). "However, bacterial infections or the activation of EGFR-Ras signaling can induce EBs to revert to a proliferative state, allowing them to re-enter the mitotic cycle." (PMID 39594605, 2024). "It is already known that acneiform eruptions occur through the inhibition of EGFR in keratinocytes, but the overlap of a bacterial infection may play an important role." (PMID 36990917, 2023). "EGFR inhibitor could dampen the innate immune system and suppress hBD2 expression, which allows bacterial infection and further results in aggravating tissue inflammation, recruiting neutrophils, and the subsequent formation of pustules." (PMID 31764850, 2019). "Taken together, these results suggest that L. rhamnosus-mediated EGFR-independent Akt activation may favor IEC activation in response to bacterial infection." (PMID 25915861, 2015). "Since EGFR is known to regulate cellular calcium response and calcium signaling is pivotal for numerous bacterial infections, we next tested whether EGFR could be involved in C. trachomatis-induced calcium release in host cells." (PMID 25471819, 2014). "The EGFR pathway is also activated in enterocytes following bacterial infection." (PMID 21176204, 2010). "In addition, L. rhamnosus promotes EGFR-independent Akt activation, which may activate intestinal epithelial cells in response to bacterial infection, in turn increasing tight junction integrity and thus enhancing the barrier function and restricting pathogen invasion." (PMID 25915861, 2015).
bacterial infection (continued). "For EGFR inhibition, the populations of dermal immune cells primarily include macrophages and mast cells; TNF-α secreted by macrophages promotes subsequent epidermal barrier defects and bacterial infections." (PMID 36204127, 2022). "In case of ECs, while EGFR/ERK components are silenced in mature ECs at the steady state, activation of EGFR/ERK signaling has been reported in response to external stress such as bacterial infection." (PMID 29719584, 2018). "At present, direct evidence for the consequence(s) of EGFR inhibition in the context of a mucosal bacterial infection is lacking." (PMID 27414801, 2016). "Moreover, L. rhamnosus promotes EGFR-independent Akt activation, which may promote activation of IPEC-J2 cells in response to bacterial infection, in turn increasing TJ integrity to optimize the barrier function and restrict pathogen invasion." (PMID 25915861, 2015).
hematological malignancies (18 papers, 2010 to 2024). "As with many solid tumors, targeting one antigen using CAR T cell therapy, including targeting EGFRVIII or EGFR, is currently insufficient to produce the drastic responses seen in hematological malignancies due to antigen escape." (PMID 39364321, 2024). "Indeed, NK-92 engineering with CARs to CD19/CD20 or disialoganglioside GD2, HER2 receptor tyrosine kinase, and epidermal growth factor receptor EGFR, disclosed higher activity against hematological malignancies or solid tumors." (PMID 32498368, 2020).
inflammation (16 papers, 2012 to 2025). Aberrant reaction of the microcirculation characterized by movement of fluid and leukocytes from the blood into extravascular tissues. "Whereas only 20% of the cases are familiar, risk factors include chronic intestinal inflammation as well as overexpression and increased activity of the epidermal growth factor receptors (EGF-R)." (PMID 31060243, 2019). "Our data, in fact, demonstrate that an increase of ceramides in these membrane fractions initially causes the activation of signalling cascades via EGFR in lung epithelium and subsequently is responsible for the induction of neutrophilic lung inflammation in vivo." (PMID 23228165, 2012). "Beyond epithelial protection, preclinical murine models reveal that EGFR-targeted therapy promotes neutrophil apoptosis and attenuates neutrophil-driven pulmonary inflammation, suggesting broader anti-inflammatory benefits." (PMID 40995116, 2025). "In addition, in a mouse model of lung inflammation, EGFR signaling and the NLRP inflammasome directly increase IL-1β levels." (PMID 36341365, 2022). "The rationale of this work was to exploit the high expression of Epidermal Growth Factor Receptor (EGFR) in fibroblast-like synoviocytes, which are the cellular component involved in the initiation and perpetuation of destructive joint inflammation." (PMID 30082640, 2018). "Activation of the EGFR pathway promotes Th2-type immune responses and TSLP release through the MEK/ERK and p38 MAPK signaling cascades, while the MAPK family (especially the p38 subtype) plays a key regulatory role in allergen-induced airway inflammation." (PMID 40605076, 2025).
metabolic disease (16 papers, 2014 to 2025). A congenital disorder (due to inherited enzyme abnormality) or acquired (due to failure of a metabolically important organ) disorder resulting from an abnormal metabolic process. "In a word, the pathogenesis of EGFR-mediated DN involves altered hemodynamic, metabolic disorders, inflammatory and immune responses, and kidney cellular dysfunction." (PMID 37789280, 2023). "Epidermal growth factor receptor (EGFR) was proposed to be involved in the pathway of metabolic disorders, and tumor necrotic factor-α (TNF-α) was regarded as an early inflammatory biomarker for MetS." (PMID 34564376, 2021). "EGFR-mediated pathway in metabolic disorders is fascinating, and EGFR inhibitors may be promising therapeutic targets for cardiovascular and metabolic diseases." (PMID 34564376, 2021). "In this study, we identified the transcription factors RXRA, EGFR, and SREBP2 precursor as key transcription factors linked to lipid homeostasis and inflammatory response from liver transcriptome profile of animal models for human metabolic diseases fed with different levels of dietary soybean oil." (PMID 35725871, 2022). "Additionally, it was found that EGFR plays an important role in non-malignant disorders and EGFR inhibitors attenuate the metabolic diseases both in vivo and in vitro studies through anti-inflammatory and anti-oxidative actions." (PMID 28460454, 2017).
benign tumors (15 papers, 2012 to 2025). "There have been documented EGFR::ZNF267 gene fusions and increased mutation rates in heteroplasmy in SH, suggesting it as a benign neoplasm." (PMID 39281855, 2024). "Most tissues (including benign tumor nodules) have a low basal level of EGFR expression, so targeting EGFR-expressing lung tumors can be an effective strategy." (PMID 30408128, 2018). "Our study showed that nuclear expression of EGFR in BOTs and LGSCs was significantly higher compared to HGSCs or benign tumours, which lends support to the molecular similarity between BOTs and LGSCs." (PMID 26870997, 2016).
neurological disorders (14 papers, 2010 to 2025). "EGFR is related to oligodendrocyte specification and is a well-established gene for treating neurological disorders." (PMID 28792504, 2017). "Similarly, the effects of AUTS2 on Drosophila EGFR signalling are compatible with a role for this protein in the regulation of Erk activity in humans, and that this effects might underline the effects of zebrafish, murine and human mutations in the onset of neurological disorders." (PMID 24348264, 2013). "In other studies, EGFR, PDGFR, and other receptor tyrosine kinases were shown to mediate neuroinflammation in various models of neurological disorders." (PMID 28558791, 2017). "While our group has described a link between EGFR signaling and YAP involving Na,K-ATPase β2-subunit/AMOG (adhesion molecule on glia) and neurofibromin-2/Merlin in cerebellar granule cells, little is known about the interaction of EGFR and YAP in neurological diseases." (PMID 39936032, 2025).
colon (13 papers, 2001 to 2025). "Several signaling pathways, such as Fas/FasL, TNFα/TNF receptor, TRAIL/TRAIL-R, and EGF/EGFR, have been suggested as therapeutic targets to induce apoptosis in gastrointestinal tract cancers." (PMID 19742123, 2009).